CXCL14 (C-X-C motif chemokine ligand 14)
Diseases named in the same sentence as CXCL14 in open-access papers (continued):
Sharing a sentence is not in itself a finding about the gene and the disease.
tumor (continued). "In contrast to previous studies in which CXCL14 was reported to be deficient in tumors and acted as a tumor suppressor, CXCL14 is recently identified as a novel potential cancer-stimulatory protein." (PMID 23294544, 2013). "In multivariate Cox regression analysis, high CXCL14 expression in tumor specimens (n = 91) from stage I/II patients was associated with increased risk for disease recurrence (risk ratio, 2.92; 95% CI, 1.15-7.40; P = 0.024)." (PMID 23294544, 2013). "Identification of the factor(s) that cause up-regulation of CXCL14 in tumor epithelial cells is another relevant issue warranting further analyses." (PMID 23294544, 2013). "Besides, we confirmed that CXCL14 in peripheral blood plasma as the biomarkers demonstrated excellent diagnostic efficacy for tumour progression." (PMID 40162549, 2025). "In summary, our study highlights the role of the differentiated stage from transitional CXCL14+ myCAFs to invasiveness‐associated myCAFs in driving tumor progression and therapy resistance in LUAD, positioning Filgotinib as a promising targeted therapy for this process." (PMID 40162549, 2025). "The levels of CXCL14 expression were closely linked to some clinicopathologic factors, including tumor-node-metastasis stage, tissue differentiation, and tumor size, which have heretofore been noted as possible predictors for the early recurrence and death of cancer." (PMID 38016990, 2023). "CXCL14 is associated with tumor stages and nodal metastasis." (PMID 37056937, 2023). "We found that CXCL14 is associated with tumor stage, OS, and RFS, suggesting that it could be an important target for treating HNSC." (PMID 34247149, 2021). "CXCL14 has been implicated as a novel immune regulator to mediate inflammatory cell migration and thus facilitate their immunological functions against pathogens and tumours." (PMID 33733587, 2021). "In tumour tissues, the loss of CXCL14 is associated with reduced infiltration of DCs, which could otherwise elicit a specific antitumor immunity." (PMID 26733763, 2016). "CXCL14 has been associated with both favourable and unfavourable outcomes depending on tumor type." (PMID 26893359, 2016). "CXCL14 is a chemokine associated with tumour development [GO:0006995], and PTDG2S whose functions are associated to lipid metabolism [GO:0006633], might be involved in controlling the proliferation rate of LGGs." (PMID 23947815, 2013). "These signaling molecules could serve as key messengers between the tumor and its microenvironment, as shown for CXCL12 and CXCL14, which are overexpressed in tumor-associated myoepithelial cells and myofibroblasts." (PMID 19187537, 2009). "CXCL14 is a highly conserved chemokine with potential roles in tumor progression and immune modulation." (PMID 42193871, 2026). "CXCL14 had low expression in normal tissue and medium expression in cancer, indicating potential involvement in tumor progression." (PMID 41511815, 2026). "Further analysis of chemokine communication revealed that CXCL14 and CX3CL1, secreted by MBT tumor cells, recruited macrophages through the CXCL14_CXCR4 and CX3CL1_CX3CR1 axes." (PMID 41322338, 2026). "To investigate the in vivo effects of CXCL14 knockdown or blockade of the CXCL14/CCR7/STAT3 axis within the tumor microenvironment (TME), we coinjected CAFs and T24 cells, each with different shRNAs, subcutaneously into nude mice." (PMID 40898244, 2025). "In summary, our results demonstrate that CXCL14 derived from CAFs within tumor tissues enhances cellular DNA damage repair in a paracrine manner, and its effect on ERCC4 is dose-dependent." (PMID 40898244, 2025). "CXCL14, a highly conserved chemokine, regulates immune cell infiltration and dendritic cell maturation, with its role in tumor growth varying by cellular origin—promoting it when derived from fibroblasts and inhibiting it when produced by epithelial cells." (PMID 40943634, 2025).
tumor (continued). "It has been mentioned previously that binding of PFKFB2 to LINC00092 maintains the glycolytic phenotype of OC cells and enhances tumor aggressiveness through interactions with CAFs that highly express CXCL14." (PMID 40045411, 2025). "the co‐injection of 3T3 Cxcl14‐OE cells with human EGFR‐mutant LUAD cells exhibited tumour proliferation and drug resistance of gefitinib and osimertinib in vivo." (PMID 40162549, 2025). "Collectively, our analysis demonstrates that transitional CXCL14+ myCAFs facilities invasion and angiogenesis, which synergistically contribute to tumour progression." (PMID 40162549, 2025). "Our findings demonstrated that CXCL14 knockdown in CAFs significantly enhanced tumor sensitivity to cisplatin, an effect that was also observed in the CCR7i and STAT3i groups." (PMID 40898244, 2025). "The expression of CXCL14 in CAFs is known to influence tumor growth and metastasis by recruiting immune cells and other cell types, thus facilitating their localization within tumor tissues." (PMID 39950116, 2025). "The results revealed that CAFs were the primary source of CXCL14 in tumor tissues, with significantly elevated expression levels observed in chemoresistant patients." (PMID 40898244, 2025). "Recent studies have indicated that CXCL14 derived from CAFs has a cancer‐promoting effect, but epithelial‐derived CXCL14 mainly inhibits tumour progression." (PMID 40162549, 2025). "Both in vitro and in vivo studies suggest that re-expressing CXCL14 can suppress tumor growth and metastasis by enhancing immune cell recruitment and modulating the tumor microenvironment." (PMID 40565366, 2025). "The plasma expression levels of CXCL14 showed significant correlation with the tumour's pathological stages, the degree of lymph node involvement (N staging) and the presence of metastasis (M staging)." (PMID 40162549, 2025). "Currently, monoclonal antibodies targeting the CXCL14/ACKR3 axis are in Phase I tumor clinical trials (NCT04857112), and our study provides a theoretical basis for expanding their indications to IPF." (PMID 40842541, 2025). "Tumor cells induce the polarization of macrophages towards the M2 phenotype via exosomal CXCL14 or microRNA (miR-let-7b), suppressing the anti-tumor immune response." (PMID 41357241, 2025). "Taken together, the consistent downregulation of CXCL14 across multiple aggressive BC subtypes and its association with shorter OS indicate that it may serve as a prognostic marker and therapeutic target, particularly through its role in immune modulation and tumor microenvironment regulation." (PMID 40565366, 2025). "Conversely, CXCL14 was highly expressed in the tumor stroma, and CAFs obtained from chemoresistant patients presented elevated CXCL14 expression." (PMID 40898244, 2025). "Immunohistochemical analyses of mouse tumours with TFRC knockdown revealed that both CXCL14 expression and the CD8+ T‐cell counts were significantly increased in the shTFRC group compared with the control group." (PMID 39095323, 2024). "A recent study reported that tumor-derived exosomes transmit CXCL14 to stimulate TAM M2 polarization through the activation of the NF-κB pathway." (PMID 39020380, 2024). "As expected, the most documented functions that are enhanced in the wake of increased CXCL14 expression are related to cellular immunity, including lymphocyte chemotaxis and tumor suppression." (PMID 38400076, 2024). "To achieve this goal, we need to better understand the mechanism of CXCL14-mediated tumor suppression and further develop effective delivery methods." (PMID 38400076, 2024). "Previous experiments have shown that tumor cell HK3 can decrease its secretion of lactate and CXCL14, indirectly impacting the polarization of macrophages toward an M2-like phenotype, thereby influencing tumor progression." (PMID 38714539, 2024).
tumor (continued). "When methylation levels were analyzed against clinical outcomes, we found 4 CpG sites around CXCL2, 16 CpG sites around CXCL12, and 3 CpG sites around CXCL14/17 where altered methylation appeared to affect tumor behavior and patients’ outcomes." (PMID 38232115, 2024). "CXCL14 gradually decreased throughout the disease process, with a particularly sharp decline in its expression level in metastatic tumor tissues, making it rather exceptional among the entire chemokine family." (PMID 39409185, 2024). "Delivery of CXCL14 and E6/E7 epitopes un- der the control of a synthetic tumor-specific promoter is a promising strategy for novel adenoviral transgene immunotherapy to treat HPV+ HNSCC." (PMID 38911052, 2024). "CXCL14 has a variety of functions, including tumor suppression, antimicrobial, anti-inflammatory, and cell migration regulation." (PMID 39334887, 2024). "We have previously shown that restoring the physiological levels of CXCL14 in HPV+ HNSCC cells significantly suppresses tumor growth in immunocompetent syngeneic mice." (PMID 38400076, 2024). "We observed a significant elevation of CXCL14 expression in tumour cells following TFRC knockdown, a result that aligns with the increased expression observed after anlotinib administration (p‐value < 0.05)." (PMID 39095323, 2024). "For example, MMP7 and CXCL14, which play important roles in tumor cell invasion and inflammation, respectively, Xenium data clearly indicated that tumor cells were responsible for their expression." (PMID 39639005, 2024). "CXCL14 exhibits tumor inhibition, antibacterial, anti-inflammatory properties, and modulates cell migration." (PMID 39334887, 2024). "Similar to CALB2, EMT, hypoxia, and inflammatory response pathways were also significantly enriched in tumor tissues with high CXCL14 expression." (PMID 39358777, 2024). "CXCL14 was clustered within the neoplasm-downregulated chemokines cluster, but its sharp downregulation during tumor metastasis particularly stands out." (PMID 39409185, 2024). "Meanwhile, Cxcl10 has inhibitory effect on tumor progression, Cxcl12, Cxcl14, Ppbp, Pf4 and Ccl8 play an important role in promoting tumor progression." (PMID 38622609, 2024). "To further investigate the role of CXCL14, we assessed CXCL14 mRNA and protein expression in tumour cells, as well as protein concentrations in the culture supernatants, following TFRC silencing in HepG2 and PLC/PRF/5 cells." (PMID 39095323, 2024). "The most interesting observation emerging from our data is that CXCL14 promotes tumor metastasis through ACKR2 in NSCLC cells." (PMID 37056937, 2023). "Future studies will further investigate this topic by evaluating tumor-infiltrating lymphocytes and CXCL14 expression in the tumor microenvironment, especially comparing CDX-2 positive cases with CDX-2 negative cases." (PMID 36928082, 2023). "Here, this study provides an overview of CXCL14 progressively upregulated along with the progression of NSCLC and associated with tumor metastasis." (PMID 37056937, 2023). "In summary, the CXCL14+ tumor cell subgroup is mainly present in BC lymph node metastasis tissues and is closely related to BC metastasis." (PMID 37858183, 2023). "The H&E stain images showed that CXCL14 overexpression increased the tumor distribution area in the left and right lung lobes, and the area in the CXCL14-KD group was lower than in the vector group." (PMID 37056937, 2023). "Previous studies have reported the pro-tumoral effects of CXCL14, based on evidence for the upregulation of CXCL14 in the tumor stroma and CAFs." (PMID 37091868, 2023). "The methylation level of CXCL14 is correlated with the anatomic site of tumor occurrence, positively correlated with patient age, and associated with prognosis." (PMID 38003215, 2023). "Further pseudotime analysis indicated that the CXCL14+ tumor cell subgroup was mainly located at the end of the differentiation trajectory and was mainly present in BC lymph node metastasis tissues." (PMID 37858183, 2023).
tumor (continued). "Chemokines, such as CCL20 and CXCL14, can recruit DCs to tumor tissue to inhibit tumor proliferation and metastasis." (PMID 36230972, 2022). "Overexpression of CXCL14 in TNBC 4T1 orthotopic mouse model significantly reduced tumor weights and inhibited lung metastasis." (PMID 36012586, 2022). "We further investigated the effects of CXCL14 on the immune-cell profiles in the tumor microenvironment using FACS analysis." (PMID 36012586, 2022). "To detect the CXCL14 production levels in tumors, we collected the total RNA of tumor tissue and performed qPCR analysis." (PMID 35439170, 2022). "Meanwhile, the IHC assay demonstrated that the expressions of CXCL14, PD-L1, and IL-10 were decreased in tumor tissues of mice treated with si-CXCL14." (PMID 35669852, 2022). "Genetic and pharmacological targeting the FGF-2/FGFR1 signaling or depletion of pericytes obliterates tumoral CXCL14 expression in FGF-2–expressing tumor–bearing mice." (PMID 35439170, 2022). "Then, si-CXCL14 and si-NC were injected intratumorally into the tumor mass every 3 days for 3 weeks." (PMID 35669852, 2022). "CAFs-derived CXCL14 affects macrophage recruitment to the tumour and shunting of their differentiation status toward the M2 subtype is associated with a bad prognosis in cancer." (PMID 36555218, 2022). "By collecting 28 pairs of PC tumor tissues and adjacent benign tissues, we first detected the mRNA abundance of CXCL14." (PMID 35669852, 2022). "Taken together, our data demonstrate that CXCL14 inhibits TNBC progression through altering immune profiles in the tumor microenvironment and it is mediated in a T cell-dependent manner." (PMID 36012586, 2022). "In conclusion, CXCL14 plays a critical role in inhibiting tumor growth and lung metastasis of TNBC in a T-cell dependent manner, through modulating the TNBC tumor immune contexture." (PMID 36012586, 2022). "The role of CXCL14 in growth inhibition and apoptosis of tumor cells, and tumor‐infiltrating lymphocytes (TIL) has been validated in human papillomavirus (HPV)‐positive head and neck cancers." (PMID 35842899, 2022). "It has been reported that, in primary HNSCC tissues, tumor cells produce a high level of CXCL12/SDF-1 and CXCL14, which promote the infiltration of tumor-infiltrating lymphocytes and pDCs." (PMID 35740551, 2022). "It has been revealed that CXCL14 inhibits tumor growth and metastasis in BC, and its protein level positively associates with OS81." (PMID 35725915, 2022). "In this study, we reported that CXCL14 was highly expressed in PC tumor tissues and positively correlated with expressions of PD-L1 and IL-10, as well as pathological stages." (PMID 35669852, 2022). "In the tumor, CXCL14 can be expressed by inflammatory cells, fibroblasts, and endothelial cells, and it stimulates its biological activities on endothelial cells, NK cells, neutrophils, DCs, and macrophages." (PMID 35439170, 2022). "In this study, we found that CXCL14 was highly expressed in PC tumor tissues, which is agreed with several previous reports." (PMID 35669852, 2022). "The tumor weights in mice bearing CXCL14 overexpression cells were significantly lower than those in mice bearing control cells at all three time points." (PMID 36012586, 2022). "We demonstrate that CXCL14 inhibits tumor growth in primary and metastatic sites in a T cell-dependent manner through altering immune cell infiltration in the tumor microenvironment." (PMID 36012586, 2022). "scRNA‐seq data revealed that malignant cells in the lymph nodes (LNs) had significantly down‐regulated CXCL14 expression compared to those in the primary tumor." (PMID 35842899, 2022). "The in vivo studies in the tumour‐bearing mouse model also showed that overexpression of CXCL14 can inhibit the tumour growth and increase NK cell infiltration." (PMID 33733587, 2021).
tumor (continued). "As expected, we also saw CXCL1, CXCL8, CXCL10, CXCL11, CXCL13, and CXCL14 in tumor tissues were upregulated in the results of TCGA data and the difference was statistically significant (p < 0.05)." (PMID 34794429, 2021). "For example, BRAK/CXCL14 is a chemokine that is constitutively produced by most tissue types but has been found to be depleted in a variety of human cancers and tumor cell lines." (PMID 34901003, 2021). "The tumor suppressive or tumor supportive roles of CXCL14 in cancer depends on the specific type of tumor." (PMID 34696665, 2021). "CXCL14 is upregulated in prostate CAFs and co-injected CXCL14-expressing fibroblasts promote xenografted tumor growth, angiogenesis and macrophage infiltration." (PMID 34681633, 2021). "Chemokine (C-X-C motif) ligand 14 (CXCL14) functions as a tumor suppressor and is significantly overexpressed in most normal tissues." (PMID 34696665, 2021). "Meanwhile, the tumour volume and weight reduced by CXCL14 overexpression were significantly increased after treatment with anti‐asialo GM1." (PMID 33733587, 2021). "CXCL14 is responsible for immune cell recruitment and maturation and is critical to upregulating major histocompatibility complex class I expression on tumor cells." (PMID 34001208, 2021). "Although few studies have investigated CXCL14, high CXCL14 expression has been found to suppress tumor growth in HNSC." (PMID 34247149, 2021). "To investigate the dysregulation of CXCL14 expression in OC cells, we measured the mRNA and protein levels of CXCL14 in 50 pairs of OC tissues and non-tumor ovarian tissues." (PMID 34789307, 2021). "If software was adopted to calculate the mean optical density of immunohistochemical staining, the value would include CXCL14 expression in both tumor cells/normal epithelial cells and stromal cells." (PMID 34744744, 2021). "On the other hand, the ligands of CXCR3, and CXCL14 and CXCL16, cause tumor infiltration by anticancer tumor-infiltrating lymphocytes (TILs) and thus show anticancer properties." (PMID 33467722, 2021). "After data processing, we also found that the expression of CXCL1, CXCL10, CXCL11, CXCL13, and CXCL14 was significantly increased in tumor tissues, and the difference between CXCL10 was the most significant." (PMID 34794429, 2021). "This clearly implies that CXCL14 is associated with disease recurrence and poor prognosis and is relevant to tumor-node metastasis (TNM) stage, differentiation grade and tumor size." (PMID 34696665, 2021). "Chemoattraction of iDCs and NK cells and functional maturation of dendritic cells by CXCL14 can substantially contribute to anti-tumor immune response." (PMID 34744744, 2021). "A more recent study, explained that the anti-tumor functions exerted by CXCL14 are carried out by means of supressing PD-L1 expression and NF-kB mediated EMT." (PMID 35047982, 2020). "Conversely, stromal cell-derived CXCL14 was frequently shown to promote tumor growth via diverse mechanisms, including epithelial to mesenchymal transition, coupled with tumor cell metastasis as well as indirect support of angiogenesis and tumor growth." (PMID 33123134, 2020). "Thomas and his colleagues have found that CXCL14 can effectively inhibit tumor angiogenesis, thereby reducing tumor cell migration." (PMID 32253815, 2020). "In recent years, CXCL14 has been shown to modulate the regulation of cellular trafficking, immune responses, cell metabolism, and tumor progression in different cell types." (PMID 32708730, 2020). "CXCL14 is a member of the ELR− chemokines isolated independently as BRAK, BMAC, or MIP-2γ from human tumor cells." (PMID 33177784, 2020). "In this study, no abnormal expression of CXCL14 was found in HNSCC tissues, but CXCL14 expression was found to be markedly related to tumor stage in patients with HNSCC." (PMID 33489879, 2020).